TWIST1 (twist family bHLH transcription factor 1)
Diseases named in the same sentence as TWIST1 in open-access papers (continued):
Sharing a sentence is not in itself a finding about the gene and the disease.
leukemia (9 papers, 2015 to 2024). A malignant (clonal) hematologic disorder, involving hematopoietic stem cells and characterized by the presence of primitive or atypical myeloid or lymphoid cells in the bone marrow and the blood. "It has been recently explored in hematological malignancies including myeloid, in which expression of Twist1 and Snail2 are associated with drug resistance, the maintenance of leukemia stem cell function, and resistance to apoptosis." (PMID 37932837, 2023). "The role of TWIST1 is not only restricted to LSCs since it has been demonstrated that TWIST1 influences bone marrow microenvironment interactions by modulating mesenchymal stem cell differentiation, which in turn promotes leukemia expansion." (PMID 39200378, 2024). "went on to further show that TWIST1 was most highly expressed in the putative leukemia stem cell (LSC) compartment in AML (CD34+CD38-) and that its expression in LSCs was higher than in normal CD34+CD38- HSCs." (PMID 37600794, 2023). "Twist1 is highly expressed in human leukemia stem cells, which maintain leukemia stem cell function." (PMID 29685144, 2018). "Taken together, these studies highlight the importance of the Twist1-Bmi1 axis in the regulation of self-renewal in both hematopoietic and leukemia stem cells." (PMID 29685144, 2018). "Downmodulation of TWIST1 reduced their colony‐forming capacity, providing further evidence for TWIST1 involvement in leukemia stem cells and disease progression." (PMID 28556516, 2017). "We then analyzed the correlation of TWIST-1 expression with other clinical characteristics of leukemia." (PMID 26023795, 2015). "Twist1 confers cancer cell self-renewal and apoptosis resistance both in solid tumors and leukemia." (PMID 29685144, 2018). "Furthermore, TWIST-1 is aberrantly highly expressed in CD34+CD38− leukemia stem cell candidates and its expression declines with differentiation." (PMID 26023795, 2015). "In addition, flow cytometry analysis showed increased apoptosis in shTWIST-1-transduced K562 cells, suggesting the important role of TWIST-1 in the survival of leukemia cells." (PMID 26023795, 2015). "Aberrantly high expression of TWIST-1 in leukemia stem/progenitor cells could be confirmed when we analyzed the expression of TWIST-1 in highly purified leukemic CD34+CD38−, CD34+CD38+ and CD34− cells isolated from patients with AML (n = 9) and CML (n = 9)." (PMID 26023795, 2015). "However, the role of TWIST-1 in AML and acute lymphoid leukemia (ALL), whether it is associated with leukemia stem cells (LSCs), and its potential pathogenic mechanism in CML remain unknown." (PMID 26023795, 2015). "TWIST1 is also essential for the viability and self-renewal of leukemia stem cells (LSCs), especially in MLL-AF9 leukemia, thus promoting disease initiation and maintenance." (PMID 39200378, 2024). "In our 3D BM niche-like AML model, leukemia cells demonstrated an upregulation of FGF2, FOS, and ERBB2, which acts on and activates Twist1 and Snail2." (PMID 37932837, 2023). "Twist1 promotes leukemia cell growth and colony formation through the Twist/c-MPL axis, and knockdown of Twist1 inhibits tumor growth." (PMID 29685144, 2018). "In other leukemia cell lines, these EMT markers were relatively in lower expressions except TWIST1 also highly expressing in THP-1." (PMID 27724883, 2016). "The findings that TWIST-1 was predominantly expressed in the leukemia stem cell candidates of AML and CML suggest a possible role of TWIST-1 in primitive myeloid leukemia cells." (PMID 26023795, 2015). "In a study involving leukemia, researchers confirmed that TRIB3 protein could bind to the WR domain of TWIST1 and contribute to its stability, by inhibiting its ubiquitination." (PMID 32874132, 2020).
metastatic carcinoma (9 papers, 2011 to 2025). A carcinoma which has spread from the original site of growth to another anatomic site. "Overexpression of Twist1 and high methylation of its promoter have frequently been found in metastatic carcinomas." (PMID 34572796, 2021). "In other studies, it has been demonstrated that TWIST1 also plays an essential role in metastatic cancer." (PMID 26359363, 2015). "Twist1, a basic helix-loop-helix transcription factor, is expressed in mesenchymal precursor populations during embryogenesis and in metastatic cancer cells." (PMID 22242143, 2011). "Twist1 promotes these cellular functions in various cell types during development, such as developing heart valves, and also in metastatic cancers." (PMID 22242143, 2011). "TWIST1 is a TF in metastatic cancer-1 cells and an EMT driver." (PMID 37853464, 2023). "Interestingly, both of TWIST1 and N-Cadherin are usually high expressed in metastatic cancer cells." (PMID 26023736, 2015). "This study investigated the role of TQ on the expression of EMT mediator proteins like Cadherins and Vimentin, and their regulatory transcription factors TWIST1, SNAIL1, SLUG and ZEB1 in metastatic cancer cell lines, as well as tumor model of mice." (PMID 26023736, 2015). "Twist1 promotes cell proliferation in ECC mesenchymal cells, in addition to other mesenchymal progenitor populations, and also in metastatic cancer cells." (PMID 22242143, 2011). "Altogether, the present study support our hypothesis that BTG2/TIS21 is a promising target to combat with metastatic cancers with high level of Twist1 without BTG2/TIS21 expression." (PMID 31138781, 2019).
liver fibrosis (8 papers, 2018 to 2021). "On the one hand, pharmaceutical inhibition and fibroblast-specific deletion of Twist1 have been shown to mitigate liver fibrosis and skin fibrosis, respectively, supporting Twist1 as a promoter of tissue fibrosis." (PMID 34869368, 2021). "Activation of TWIST transcription by BRG1, a chromatin remodeling protein, was suggested to contribute to liver fibrosis in mice and a TWIST1 inhibitor (harmine) exerted anti-fibrogenic effects." (PMID 34588551, 2021). "Genetic deletion of MKL1 in endothelial cells or pharmaceutical inhibition of MKL1 or STAT3 or TWIST1 is sufficient to alleviate liver fibrosis in mice." (PMID 31776330, 2019). "Here we delineate a novel pathway underlying TGF-β induced EndMT and liver fibrosis in which the transcriptional modulator MKL1, in cooperation with the transcription factor STAT3 to activate TWIST1 transcription." (PMID 31776330, 2019). "Recent studies showed that Twist1 expression and its role in liver fibrosis seem to be contradictory." (PMID 29314610, 2018). "Finally, direct inhibition of TWIST1 by a small-molecule compound harmine was paralleled by blockade of EndMT in cultured cells and liver fibrosis in mice." (PMID 31776330, 2019). "To determine whether Twist1 regulates miR-214 expression in HSCs and in liver fibrosis models, we overexpressed Twist1 in rat HSCs or LX2 using lentiviral vectors containing GFP." (PMID 29915227, 2018). "This study also showed that Twist1 might regulate miR‐214‐5p to activate HSCs and promote the progression of liver fibrosis." (PMID 29314610, 2018). "Now that STAT3 appeared to be essential in recruiting MKL1 to activate Twist1 transcription, we tested the hypothesis that STAT3 inhibition might serve to attenuate liver fibrosis." (PMID 31776330, 2019). "We finally examined whether pharmaceutical inhibition of TWIST1, the end-product of the STAT3-MKL1 transcriptional axis, would be sufficient to attenuate EndMT and liver fibrosis." (PMID 31776330, 2019). "In conclusions, the Twist1-regulated miR-214 promotes the activation of HSC cells through targeting Sufu involved in the Hedgehog pathway and participates in the development of hepatic fibrosis." (PMID 29915227, 2018).
papillary thyroid cancer (8 papers, 2013 to 2022). "Of note, among the downregulated genes MMP2, VEGFA, CCND1, and TWIST1 were downregulated only in papillary carcinoma but were either unchanged or upregulated in other two subtypes." (PMID 30863721, 2019). "Here, using miRNome profiling of papillary thyroid cancer cells (TPC-1) ectopically expressing TWIST1, we identified miR-584." (PMID 27661106, 2016). "In papillary thyroid carcinoma, ETV5 is highly expressed and can promote the expression of the twist-related protein 1 (TWIST1) gene, which has been shown to induce the EMT process." (PMID 34736492, 2021). "The study conducted by Gugnoni indicated that accumulated P62 might ubiquitinate Twist1 to promote the stabilization of Twist1 and the EMT in papillary thyroid carcinomas." (PMID 30832706, 2019).
prostate tumor (8 papers, 2010 to 2025). "Our finding shows a significant association of TWIST1 mRNA upregulation with metastatic prostate tumor tissues compared to normal and primary prostate tissues." (PMID 31060254, 2019). "TWIST1 functioning as a transcription factor co-expressed with HOXA9 was activated in prostate tumors, research further showed that TWIST1, WDR5 and the lncRNA HOTTIP formed a complex and regulated the chromatin in the promoter of HOXA9." (PMID 36376832, 2022). "On the contrary, the expression level of Twist1 was markedly increased in prostate tumor specimens and positively correlated with clinical grade." (PMID 27121312, 2016). "We quantified TWIST1 expression in a panel of patient derived material, comprising 21 normal prostate samples (adjacent to cancer), 74 primary prostate tumors, of which 9 hormone-refractory samples, and 13 lymph node metastasis." (PMID 20976069, 2010). "Twist1 expression is increased in malignant as compared to non-malignant prostate tissues and prostate tumors with high Gleason grades exhibit high Twist1 protein levels." (PMID 32296610, 2020). "In MPS containing prostate tumor spheroids, we observed upregulation of EMT-related transcription factors GLI and TWIST1, compared to MPS without tumors." (PMID 40596459, 2025).
Insulin resistance (7 papers, 2012 to 2023). Increased resistance towards insulin, that is, diminished effectiveness of insulin in reducing blood glucose levels. "Moreover, Twist1 expression is strongly correlated with BMI and insulin resistance in humans." (PMID 22969750, 2012). "Previous studies have reported that Twist1 is most abundantly expressed in the WAT and BAT in adult mice, and that its expression is negatively correlated with the homeostasis model assessment of insulin resistance (HOMA-IR) and adipocyte size in human." (PMID 37784111, 2023). "The distribution pattern of TWIST1 and TWIST2 seems to be different; the levels of TWIST1 are higher in subcutaneous adipose tissues compared to visceral adipose tissues, which is strongly correlated with BMI and insulin resistance, while Twist2 is more ubiquitously expressed in the body." (PMID 34660572, 2021).
oral cancer (7 papers, 2014 to 2021). "Furthermore, Shp2 promotes invasion and metastasis of oral cancer cells; this result indicated that the Shp2-ERK1/2-Snail/Twist1 pathway is possibly implicated in oral cancer invasion and metastasis." (PMID 26088100, 2015). "In the presence of a selective ERK1/2 inhibitor, FR180204, we observed a dose-dependent reduction at the transcript levels of Snail/Twist1 in oral cancer cells." (PMID 24931737, 2014). "Our result indicated that the downregulatory effects of SHP2 on ERK1/2 might regulate Snail/Twist1 mRNA expression and play a crucial role in oral cancer invasion and metastasis." (PMID 24931737, 2014). "We observed that SHP2 promotes the invasion and metastasis in oral cancer, and identified an ERK1/2-Snail/Twist1 pathway mediated by SHP2 that might play a major role in oral cancer invasion and metastasis." (PMID 24931737, 2014). "Alternatively, Snail/Twist1 may be involved in steps other than the EMT during oral cancer progress." (PMID 24931737, 2014). "A panel of oral cancer human cell lines (SCC9, SCC25, and OSCC1.2/RBT3) where TWIST1 is overexpressed or knockdown, as well as normal immortalized oral epithelial cells (NOE) established from human tongue, were investigated as a preclinical model." (PMID 33466385, 2021). "To investigate the functional role of TWIST1 in OSCC, we studied this gene in a syngeneic model using the murine oral carcinoma cell line (AT84), which expresses high levels of TWIST1 and also a highly metastatic human cell line (OSCC1.2/RBT3) using nude mice." (PMID 33466385, 2021). "Notably, both expressions of TWIST1 and ZEB2 have been reported to be of significant prognostic value in early stage colorectal and oral cancer patients where disease spread is not always evident." (PMID 26214683, 2015).
oral squamous cell carcinoma (7 papers, 2012 to 2025). "The co-expression of ZEB2 and TWIST1 has been previously reported in patients with oral squamous cell carcinoma." (PMID 35884488, 2022). "In addition, co-expression of TWIST1 and ZEB2 was observed in patients with oral squamous cell carcinoma and was significantly associated with poor survival." (PMID 35884488, 2022). "However, it remains unclear whether there is a direct link between ZEB2 and TWIST1 in oral squamous cell carcinoma and other carcinomas." (PMID 35884488, 2022).
adenoma (6 papers, 2012 to 2022). A neoplasm arising from the epithelium. "In 2010, a Japanese study reported increased TWIST1 methylation levels in CRCs and adenomas vs. normal mucosa (median 55.7%, 25.6%, and 0.0%, respectively), and methylated TWIST1 was suggested to be a potential biomarker in early CRC, with 89.6% of accuracy." (PMID 34768901, 2021). "Through two novel transgenic mouse models, we show that Twist1 cooperates with KrasG12D to markedly accelerate lung tumorigenesis by abrogating cellular senescence programs and promoting the progression from benign adenomas to adenocarcinomas." (PMID 22654667, 2012). "Because we frequently observed hypermethylation of TWIST1 in the tissues of colorectal adenoma and cancer, we thought methylated TWIST1 would be available as a biomarker of blood-based DNA testing for the detection of colorectal neoplasia including adenoma and cancer." (PMID 29682198, 2018). "The median copy numbers of methylated TWIST1 were 0.0 (range, 0 to 11.4) in the control group, 1.9 (range, 0 to 11.2) in the non-advanced adenoma group, 1.7 (range, 0 to 26) in the advanced adenoma group, and 1.8 (range, 0 to 330) in the CRC group." (PMID 29682198, 2018). "In conclusion, the combination of TWIST1 methylation analysis by serum CORD assay and FIT showed higher sensitivities for the detection of non-advanced adenoma, advanced adenoma, and early-stage CRC without great difference in the specificity as compared to those by FIT alone." (PMID 29682198, 2018).
clear cell renal cell carcinoma (6 papers, 2013 to 2025). "We aimed to determine prognostic value of six key EMT markers (CDH1, CDH2, SNAI1, SNAI2, VIM, TWIST1) in clear cell renal cell carcinoma (ccRCC)." (PMID 31915310, 2020).
diabetic kidney disease (6 papers, 2021 to 2026). Progressive kidney disorder caused by vascular damage to the glomerular capillaries, in patients with diabetes mellitus. "Triptolide targets autophagy through the mTOR/Twist1 pathway and inhibits the epithelial-mesenchymal transition of podocytes in diabetic nephropathy." (PMID 41536046, 2025). "Tripterygium wilfordii and its active components upregulate autophagy in diabetic kidney disease (DKD) mice through the mTOR/Twist1 signaling pathway, reduce podocyte transdifferentiation and apoptosis, reduce interleukin-4 overexpression, enhance cell viability, and inhibit podocyte apoptosis." (PMID 36003509, 2022). "IHC staining of these biopsies revealed induction of Twist1 in glomerular podocytes during FSGS, IgA nephropathy, and diabetic nephropathy (DN) compared with controls." (PMID 34369383, 2021). "Moreover, TWIST1 has been reported to play an intermediate role between EMT and autophagy in cancers and diabetic kidney disease." (PMID 37403096, 2023). "Recent studies have shown that in DKD, tripterygium glycoside attenuates EMT and apoptosis in diabetic kidney disease, by upregulating autophagy through the mTOR/Twist1 signalling pathway." (PMID 35560773, 2022).
endometriosis (6 papers, 2015 to 2026). The growth of functional endometrial tissue in anatomic sites outside the uterine body. "The role of EMT and proliferation in the pathogenesis of endometriosis was evaluated by analyzing TWIST1, CDH1 and MYC expression." (PMID 26198055, 2015). "In our study of 110 endometriosis patients, we discriminated between epithelial and stromal protein expression by using IHC analysis for TWIST1 and MYC." (PMID 26198055, 2015). "Few data exist that indicate a potential role of TWIST1 in the pathogenesis of endometriosis." (PMID 26198055, 2015). "Thus, we excluded a simultaneous upregulation of TWIST1 and MYC that may orchestrate the cellular changes associated with invasion and proliferation in endometriosis." (PMID 26198055, 2015). "In conclusion, epithelial TWIST1, SOX15, and OCT4 are overexpressed in endometriotic tissue compared to EP endometrium of paired and unpaired endometriosis samples." (PMID 27881125, 2016). "Immunohistochemical analysis was used to determine stromal and epithelial expression of OCT4, SOX15, TWIST1 and DCAMLK1 in endometriosis patient (EP) endometrium (n = 69) and endometriotic tissue (n = 90) and in control endometrium (n = 50)." (PMID 27881125, 2016). "We showed a significant inverse expression between TWIST1 and CDH1 in controls and eutopic and ectopic tissue of endometriosis patients." (PMID 26198055, 2015). "CDH1, TWIST1, SNAIL and SLUG mRNA expression was analyzed by qRT-PCR from 47 controls and 74 patients with endometriosis." (PMID 26198055, 2015). "Our findings suggest that the enhanced expression of TWIST1, SNAIL and SLUG in ectopic lesions plays a crucial role in the formation and maintenance of ectopic lesions in endometriosis." (PMID 26198055, 2015). "We found that TWIST1, SNAIL and SLUG are overexpressed (p < 0.001, p = 0.016 and p < 0.001) in endometriosis, while CDH1 expression was concordantly reduced in these samples (p < 0.001)." (PMID 26198055, 2015). "In conclusion, the results reported herein suggest that in endometriosis SOX15 and TWIST1 may be stemness-related markers as their expression correlates with OCT4 expression." (PMID 27881125, 2016). "It seems that a high expression of TWIST1, which was shown to be associated with the stemness marker OCT4 in endometriosis, excludes a high expression of MYC, which is associated with proliferation in endometriosis." (PMID 26198055, 2015). "In addition, the inclusion of markers previously identified in the peripheral blood of endometriosis patients—such as SNAIL1, SNAIL2, TWIST1, and ZEB1 —could improve our understanding of the systemic aspects of the disease." (PMID 39857742, 2025). "Although both were upregulated, TWIST1 and MYC were not expressed concurrently, which suggest that in cells with high MYC expression, an additional upregulation of TWIST1 and vice versa seems to provide no further advantage for the development of endometriosis." (PMID 26198055, 2015). "The aim of this study was to determine the presence and distribution of the stemness-related factors OCT4, SOX15, TWIST1 and DCAMLK1 in women with and without endometriosis." (PMID 27881125, 2016).